LEP (leptin)
Diseases named in the same sentence as LEP in open-access papers (continued):
Sharing a sentence is not in itself a finding about the gene and the disease.
hyperlipidemia (continued). "To explore the mechanism linking maternal hyperlipidemia with elevated blood pressure in offspring, we examined the serum leptin levels in offspring at different ages in a rat model." (PMID 33431976, 2021). "Our data indicate that increased leptin levels and leptin promoter hypomethylation were present in adipose tissues from rat offspring born to maternal hyperlipidemia." (PMID 33431976, 2021). "The positive correlations between leptin and all anthropometric parameters were found in both the obese hypertensive group and the mild hyperlipidemia group." (PMID 32085704, 2020). "Here we report that the FXN knock-in/knock-out (KIKO) mouse shows hyperlipidemia, reduced energy expenditure and insulin sensitivity, and elevated plasma leptin, recapitulating T2D-like signatures." (PMID 31974344, 2020). "On the other hand, hepatic hypertrophy and hyperlipidemia were observed in both obese rats, and concomitantly, serum leptin and insulin were higher in fatty rats than in lean rats." (PMID 32041091, 2020). "Investigations on the relationship between leptin and hyperlipidemia and between hyperlipidemia and gallstones showed some indications of the associations between them, but they remain still unclear." (PMID 29088261, 2017). "We investigated the associations of LEP G2548A and LEPR Q223R polymorphisms with statin-induced creatine kinase (CK) elevation among Chinese patients with hyperlipidemia." (PMID 29296187, 2017). "Here, the effects of ASI on prevention of the development of hyperlipidemia and alleviation of leptin resistance in high-fat diet (HFD)-fed C57BL/6 mice and db/db mice were investigated and the possible underlying mechanisms were discussed." (PMID 27444146, 2016). "Based on the decreasing leptin concentrations after metformin administration in the patients with PCOS, our data seem to support the occurrence of hyperlipidemia, which is a state of leptin resistance or tolerance, in the patients with PCOS." (PMID 26473366, 2015). "Secondly, leptin level is selective item of routine physical examination, usually was chosen by subjects who are aware of overweight or hyperlipidemia." (PMID 21526991, 2011). "In addition, higher levels of serum TC, TG, LDL-C, and leptin were observed in the offspring of HALEs group, indicating that maternal ALEs-rich diet induced hyperlipidemia." (PMID 38962449, 2024). "Leptin may contribute to hyperlipidemia through the OB-R-mediated activation of the JAK2/STAT3 pathway, which affects lipid metabolism and fat deposition in hepatic tissue." (PMID 36539694, 2022). "Leptin in the periphery reduces fat deposition, which contributes to hyperlipidemia improvement." (PMID 36539694, 2022). "Using the measured dynamics of plasma leptin, we also tested the hypothesis that a diurnal increase in lipid uptake (and therefore decreased lipemia) would be related to adipokine concentrations." (PMID 34369385, 2021). "Since BAT is a major sink for circulating nutrients, including lipids, when activated by cold, the anti-hyperlipidemia effects of leptin in LD might be partly attributable to increased BAT thermogenesis." (PMID 34444659, 2021). "Leptin reduction is due to decreasing the fat mass in the body by the psyllium husk extract’s hypolipidemic effect, leading to attenuation of the proinflammatory environment accompanying hyperlipidemia." (PMID 33923513, 2021). "Past studies have related diurnal patterns of plasma leptin concentrations with hyperlipidemia." (PMID 34369385, 2021). "Most intriguingly, leptin treatment can mitigate IH-induced hyperlipidemia and cardiovascular outcomes in lean, wild type suggesting that a boost in leptin signaling may prevent downstream cardiometabolic consequences of IH." (PMID 30127766, 2018). "Therefore, the objective of this study was to evaluate possible links between leptin, hyperlipidemia, and the development of cholelithiasis in dogs." (PMID 29088261, 2017).
hyperlipidemia (continued). "In this study, we examined the differences in leptin, leptin receptor, total cholesterol, and triglyceride levels between healthy dogs and dogs with cholelithiasis, and evaluated the correlation between leptin and hyperlipidemia." (PMID 29088261, 2017). "However, further studies are required to definitively elucidate the relationship between hyperlipidemia and leptin in the pathophysiology of gallstones disease." (PMID 29088261, 2017). "Starvation, however, is also characterized by hyperlipidemia, at least in the blood stream, and the ability of triglycerides to induce leptin resistance during famine counter the leptin-induced shift toward use of triglycerides as an energy source and so helps to conserve fat stores." (PMID 26041981, 2015). "These were associated with higher leptin levels but not with hyperlipidemia." (PMID 37960308, 2023). "Thus, we propose that the leptin/JAK2/STAT3 pathway may be the regulatory target of COE in hyperlipidemia treatment." (PMID 36539694, 2022). "Thus, quercetin may mediate the role of COE in the leptin/OB-Rb/JAK2/STAT3 pathway in a rat model of hyperlipidemia." (PMID 36539694, 2022). "The existing literature has documented the impaired secretion of leptin and adiponectin in NAFLD and hyperlipidemia models." (PMID 40565688, 2025). "COE activates the leptin/JAK2/STAT3 pathway, leading to an improvement in liver function and lipid metabolism and ultimately alleviating hyperlipidemia in rats." (PMID 36539694, 2022). "In addition, because adiponectin is considered a functional leptin antagonist, subsequently, the reduction of leptin suggests a possible improvement in adiponectin’s activity: insulin sensitivity, adequate adipogenesis, and amelioration of hyperlipidemia showing lipid homeostasis." (PMID 32120804, 2020). "The amelioration of hyperlipidemia and decreased body weight after CM treatment (data not presented) were accompanied by a significant decrease (p < 0.0001) in serum leptin and increased (p < 0.0001) circulating adiponectin levels in the NAFLD+CM group in comparison to the NAFLD group." (PMID 34306045, 2021). "One study showed that the associations between leptin and lipid [low-density lipoprotein (LDL), high-density lipoprotein (HDL), total cholesterol, and triglyceride] levels were not statistically significant in patients with combined hyperlipidemia." (PMID 29088261, 2017). "In the case of reported patient with CD, PSC, and HT, the morbid obesity without any hyperlipidemia could be due to central leptin resistance." (PMID 22927860, 2012). "Moreover, hyperlipidemia–induced dysbiosis can lead to disorder of the local immune system, accompanied by production of inflammatory cytokines such as IL–1β, IL–6, and tumor necrosis factor (TNF)–α, and adipokines such as leptin in addition to increasing the intestinal permeability." (PMID 36364184, 2022). "Moreover, we investigated whether FFAs affected leptin expression and TET1 expression in PA-treated rat MSCs during adipogenic differentiation, to further substantiate the reprogramming of leptin in adipose tissue by intrauterine hyperlipidemia." (PMID 33431976, 2021).
Cognitive impairment (93 papers, 2007 to 2026). Abnormal cognition is characterized by deficits in thinking, reasoning, or remembering. "We also demonstrated that leptin supplementation during lactation prevents the cognitive deficits associated with HFD‐induced MONW, offering a potential early‐life intervention strategy." (PMID 40944384, 2025). "The Framingham Heart Study reported that higher leptin levels were associated with a lower risk of cognitive impairment and higher brain volume, a surrogate marker of brain health." (PMID 41017217, 2025). "Numerous studies designated that low plasma leptin level was associated with cognitive impairment and AD development." (PMID 40498212, 2025). "Adiponectin reduces inflammatory markers and enhances insulin sensitivity, whereas leptin resistance can induce cognitive impairment by activating inflammatory signals and causing endoplasmic reticulum stress in the hypothalamus." (PMID 41488045, 2025). "This provides renewed hope for individuals suffering from cognitive impairments associated with leptin resistance and metabolic dysfunction." (PMID 39594988, 2024). "Increased levels of Hcy and SHBG and decreased leptin are strongly associated with the occurrence of cognitive impairment in SCZ cases." (PMID 39554652, 2024). "The study results suggest that a decreased level of leptin is potentially associated with cognitive impairment in patients with SCZ." (PMID 39554652, 2024). "and leptin is considered to be an early indicator of cognitive impairment, with higher leptin levels associated with poorer cognitive functioning, especially in attentional inhibition control tasks." (PMID 35265020, 2022). "Their results suggest that older adults with low or high circulating leptin concentrations are particularly prone to cognitive impairment and point to leptin as a modifiable risk factor." (PMID 35563589, 2022). "Alterations in hormones involved in MS, such as leptin and adiponectin, are also linked to cognitive impairment." (PMID 34208833, 2021). "Recent studies in animal models show that leptin deficiency or resistance is associated with cognitive disorders, such as reductions in LTP, long-term neuronal depression (LTD), and alterations in spatial memory." (PMID 34208833, 2021). "Insulin and leptin play pivotal roles in the regulation of immunometabolism in the CNS and periphery, and dysfunction of these signaling pathways are associated with cognitive impairment." (PMID 34795562, 2021). "Leptin resistance in AD is associated with diminished activity in these pathways and increased cognitive impairment." (PMID 34208833, 2021). "We found a non-linear U-shaped relationship between circulating leptin and cognition, with both lower and higher concentrations of leptin being associated with more severe cognitive impairment in community-dwelling older Asians." (PMID 30893833, 2019). "Certain adipocytokines including leptin and adiponectin were reported to medicate early cognitive impairment caused by IR." (PMID 31651303, 2019). "Our main finding was that, independent of all measured potential confounders, both lower and higher concentrations of leptin were associated with more severe cognitive impairment among community-dwelling older adults, specifically affecting episodic memory." (PMID 30893833, 2019). "Population-based studies indicate that decreased leptin levels are associated with cognitive impairment, while higher leptin levels were associated with a lower risk of dementia." (PMID 28442988, 2017). "Chronic elevation of leptin in obese individuals probably results in leptin resistance which is associated with cognitive deficits and inability to regulate weight." (PMID 24391586, 2013). "More recently, low leptin levels have been implicated as a direct cause of cognitive impairment, particularly AD." (PMID 22701480, 2012). "More recently, low leptin levels have been implicated as a direct cause of cognitive impairment, particularly Alzheimer’s disease (AD)." (PMID 21070531, 2010).
Cognitive impairment (continued). "Several lines of evidence have implicated dysregulation and/or deficiencies in the leptin system in the cognitive deficits associated with neurodegenerative disorders such as Alzheimer's disease." (PMID 18024215, 2007). "Moreover, as the hippocampus is a key site for degeneration in AD, the regulatory actions of leptin are also crucial in age-related neurodegenerative disorders associated with cognitive deficits." (PMID 41462981, 2025). "Based on these observations, we hypothesize that disrupted leptin signaling underlies the cognitive impairments observed in HFD OPFR-treated females." (PMID 40863915, 2025). "The therapeutic potential of leptin has been proven by studies demonstrating that supplementation with the hormone can reverse cognitive deficits in leptin-deficient models, in addition to its broader neurotrophic effects in regions such as the cerebellum and anterior cingulate gyrus." (PMID 39594988, 2024). "Thus, addressing leptin resistance and its impact on hippocampal function is crucial for understanding and mitigating cognitive impairments associated with metabolic disorders and aging." (PMID 39594988, 2024). "Several studies found that leptin resistance is associated with cognitive deficits." (PMID 35739547, 2022). "Reduced leptin release caused by infection may also compromise CNS-mediated control of energy homeostasis, further enhancing the risk of MetS-associated cognitive impairment." (PMID 34795562, 2021). "Moreover, cognitive deficits in a 5-year-old child, who was unable to produce leptin due to a leptin (ob) gene mutation, also markedly improved in response to a leptin treatment strategy." (PMID 33440796, 2021). "However, studies in humans are controversial since available information for the association of adiponectin and leptin levels in the blood and CSF with cognitive impairment is inconclusive." (PMID 34208833, 2021). "Leptin’s observed role in neurogenesis and learning raises questions about whether leptin deficiency is a mediator of cognitive deficits observed in AN." (PMID 32760588, 2020). "Leptin signaling dysfunction has been associated to central complications, including cognitive impairment or long-term potentiation, and therefore, we cannot exclude our findings that it might be at least partially due to altered leptin signaling." (PMID 32264944, 2020). "Leptin levels might be related to cognitive impairment in FEP patients; however, causal mechanisms of this association need to be confirmed." (PMID 32547431, 2020). "This suggests that older adults with both lower and higher circulating leptin concentrations are particularly prone to exhibit cognitive impairment for which leptin may be a modifiable risk factor." (PMID 30893833, 2019). "This U-shaped relationship suggests that older adults with low or high circulating leptin concentrations are particularly prone to exhibiting cognitive impairments for which leptin may be a modifiable risk factor." (PMID 30893833, 2019). "This was also supported by other recent observations showing that low levels of leptin, leptin resistance, or leptin receptor deficiency in the hippocampus of diabetic rodents may be involved in cognitive deficits." (PMID 28621759, 2017). "Released by adipose tissue, leptin is present in much higher concentrations in obese individuals, often leading to leptin resistance which has been associated with cognitive deficits." (PMID 28093279, 2017). "The down-regulation of leptin/LepRb signaling might be associated with depressive-like behavior and cognitive impairment in obese rats facing chronic mild stress." (PMID 27739518, 2016). "Because of the interference in leptin functions and leptin resistance, this hormone cannot exert its beneficial effects on nerve cells in obese subjects on high-fat diet and the risk of cognitive disorders, such as Alzheimer's may increase in these people." (PMID 24592306, 2014).
Cognitive impairment (continued). "In this way a paradoxical situation takes place: leptin is a neuroprotective factor, counteracting AD cognitive impairment, as confirmed by the clinical observation that a weight loss precedes AD manifestations and is accompanied by reduced serum levels of leptin." (PMID 22701480, 2012). "Based on our previous findings, we hypothesize that early HFD intake induces transcriptomic changes associated with cognitive impairment, that these alterations are prevented by perinatal leptin intake, and that such changes can be detected both in the hippocampus and PBMC." (PMID 40944384, 2025). "Clinical findings indicate that insulin and leptin resistance are related to cognitive deficits and neuropsychiatric disorders, and interestingly, these analyses propose that the associated deficits in neuroplasticity can be reversed by restoration of insulin and leptin sensitivity." (PMID 36674935, 2023). "Hence, we investigated whether plasma levels of adiponectin and leptin are associated with future cognitive decline and cortical thinning across Aβ conditions (Aβ [+] and Aβ [−]) in individuals with mild cognitive impairment (MCI)." (PMID 36329496, 2022). "Leptin levels might be associated with cognitive deficits in FEP patients." (PMID 32547431, 2020). "Based on the present findings, one can speculate that altered leptin signaling may compromise the development of GABAergic transmission, to at least partly underlie cognitive deficits and neurological disorders associated with leptin deficiency or leptin resistance." (PMID 25177272, 2014). "The ability of leptin to promote rapid changes in neuronal morphology may be critical for its role in both normal CNS function and in neurological diseases associated with leptin resistance and cognitive deficits." (PMID 17618127, 2007). "This study aims to investigate the role of leptin in the connection between adipose-derived inflammatory signaling and cognitive impairment/NPS." (PMID 40521397, 2025). "Lower plasma leptin levels have been reported in individuals with mild cognitive impairment or Alzheimer’s Disease compared to controls." (PMID 40607230, 2025). "In regard to the prevention of AD and related cognitive impairment among older adults, more attention needs to be paid to maintaining appropriate leptin levels." (PMID 38700863, 2024). "In line with the observed protective effects of leptin at hippocampal synapses, there is now good evidence that leptin also alleviates AD-driven cognitive impairments reported in various rodent models of AD." (PMID 39000459, 2024). "In this study we analyzed the relationship between serum leptin and adiponectin levels and the onset or progression of brain infarcts in subjects with mild cognitive impairment (MCI) and Alzheimer’s disease (AD)." (PMID 38686200, 2024). "In-field research demonstrates the therapeutic potential of leptin analogs and sensitizers, which can be potentially beneficial for cognitive deficits in both rodents and humans, albeit complicated by the phenomenon of leptin resistance." (PMID 39594988, 2024). "Such disruptions contribute to the cognitive deficits, including memory impairment and compromised spatial learning, frequently observed in individuals with leptin resistance." (PMID 39594988, 2024). "Over 50% of subjects with mild cognitive impairment showed lower leptin levels than the control group." (PMID 38933275, 2024). "Complementary interventions such as caloric restriction and physical exercise also enhance leptin sensitivity and offer potential benefits to alleviating cognitive impairments." (PMID 39594988, 2024). "Leptin effectively improved these behavioral alterations including cognitive impairments and depressive-like conducts." (PMID 36674935, 2023). "In particular, a higher circulating leptin level results in a higher cerebral brain volume, which is inversely correlated with cognitive impairment." (PMID 36904288, 2023).